CARMN (cardiac mesoderm enhancer-associated non-coding RNA)
Synonyms: CARMEN; formerly MIR143HG
Gene: Long non-coding RNA gene on chromosome 5 (149,406,609 to 149,432,835, forward strand). Ensembl gene ENSG00000249669.
Gene Ontology:
Biological process: miRNA-mediated post-transcriptional gene silencing
Cellular component: RISC complex
Diseases named in the same sentence as CARMN in open-access papers:
CARMN is named in the same sentence as 21 diseases in open-access papers, as found by Europe PMC text mining. Sharing a sentence is not in itself a finding about the gene and the disease. The quoted sentences say what the papers report.
breast carcinoma (4 papers, 2020 to 2024). "In breast cancer, CARMN is significantly downregulated, and its expression levels are closely associated with patient outcomes, establishing CARMN as a crucial predictive biomarker for this disease." (PMID 39199342, 2024). "CARMN was differently expressed in different subtypes of breast cancer, in which TNBC has the lowest expression of CARMN and luminal A breast cancer has the highest expression of CARMN." (PMID 34162418, 2021). "Upregulation of CARMN is a strong predictor of longer relapse free survival and overall survival in all breast cancer cohort and local advanced breast cancer cohort." (PMID 34162418, 2021). "High expression of CARMN was also related with better prognosis in breast cancer patients, especially in patients with TNBC." (PMID 34162418, 2021). "DNA replication related DEGs were negatively correlated with CARMN expression in TCGA breast cancer cohort especially in TNBC cohort." (PMID 34162418, 2021). "In TCGA dataset, CARMN was downregulated in each stage of breast cancer comparing with normal samples." (PMID 34162418, 2021). "On the other hand, low expressions of LINC01279, RAD51-AS1 and CARMN were correlated with significantly worse OS in breast cancer patients." (PMID 33128008, 2020). "High expression of MAD2L1, CCNA2 and FUT8-AS1 and low expressions of LINC01279, RAD51-AS1 and CARMN were correlated with significantly worse OS in breast cancer patients, while Other candidate hub genes expression were not significantly relevant to OS." (PMID 33128008, 2020). "Additionally, CARMN functions as a tumor suppressor in cancers such as hepatocellular carcinoma, bladder cancer, and breast cancer, where its regulatory roles in cell invasion, migration, and proliferation highlight its potential as a beneficial biomarker and therapeutic target." (PMID 39199342, 2024). "Moreover, we also identified a significant upregulation of CARMN in ER- breast cancer with pCR." (PMID 34162418, 2021). "Besides breast cancer, CARMN is also significantly downregulated in many other cancers." (PMID 34162418, 2021). "On the other hand, CARMN, PRINS and MEG3 probably have an important role in pathogenesis of all subtypes of breast cancer." (PMID 33128008, 2020).
atherosclerosis (3 papers, 2024 to 2025). A disease characterized by the build-up of fatty material and calcium deposition in the arterial wall resulting in partial or complete occlusion of the arterial lumen. "By investigating the mechanism by which CARMN regulates atherosclerosis, we found that silencing CARMN regulates autophagy in VSMCs, thereby accelerating atherosclerotic progression in vivo." (PMID 41213929, 2025). "Collectively, our previous experimental results indicate that silencing CARMN promotes atherosclerosis; therefore, we conclude that silencing CARMN regulates autophagy in VSMCs to accelerate atherosclerotic progression in vivo." (PMID 41213929, 2025). "Other studies have shown that CARMN is specifically expressed in VSMCs and that its expression progressively decreases with the progression of atherosclerosis." (PMID 41213929, 2025). "Kyoto Encyclopedia of Genes and Genomes (KEGG) enrichment analysis of the resulting DEGs revealed significant enrichment in the “lipid-atherosclerosis” pathway, suggesting that CARMN modulates lipid metabolism in vitro." (PMID 41213929, 2025). "A recent study confirmed that CARMN is located mainly in the nucleus and could be involved in the development of atherosclerosis by regulating the expression of adjacent genes." (PMID 41213929, 2025). "However, in vitro experiments revealed that exogenous supplementation with miR-145 and miR-143 did not fully reverse the proatherogenic effects induced by CARMN silencing, suggesting that CARMN knockdown may promote atherosclerosis progression through additional mechanisms." (PMID 41213929, 2025). "However, in vitro experiments revealed that exogenous supplementation with miR-145 and miR-143 did not completely reverse the proatherogenic effects induced by CARMN silencing, suggesting that CARMN knockdown may promote atherosclerosis progression through additional mechanisms." (PMID 41213929, 2025). "To confirm whether CARMN plays a role in atherosclerosis by regulating CSNK1A1 expression, we stimulated VSMCs with ox-LDL and detected the expression of CARMN and CSNK1A1 using qRT-PCR." (PMID 41213929, 2025). "In summary, as shown in the schematic diagram, our study demonstrated that CARMN knockdown suppressed CSNK1A1 expression, thereby promoting VSMC-derived foam cell formation and atherosclerosis via the transcriptional downregulation of autophagy mediated by the AKT/ATG7 pathway." (PMID 41213929, 2025). "Additionally, CARMN interacts with serum response factor (SRF) to regulate VSMC plasticity, significantly impacting the progression of atherosclerosis." (PMID 38597937, 2024). "Second, although we demonstrated that knockdown of CARMN resulted in significant downregulation of CSNK1A1 in vivo, we did not directly validate the biological role of CSNK1A1 in atherosclerosis." (PMID 41213929, 2025).
bladder cancer (2 papers, 2020 to 2024). "CARMN (also known as MiR143HG) is recognized as a tumor suppressor in bladder cancer." (PMID 33128008, 2020).
hepatocellular carcinoma (2 papers, 2020 to 2024). A malignant tumor that arises from hepatocytes. "CARMN was significantly down-regulated in hepatocellular carcinoma (HCC) tissues and cells." (PMID 33128008, 2020).
psoriasis (2 papers, 2021 to 2023). An autoimmune condition characterized by red, well-delineated plaques with silvery scales that are usually on the extensor surfaces and scalp. "To experimental validate the immunoregulatory potential of cell-type specific lncRNAs, we selected three lncRNAs (SNHG9, CALML3-AS1, and CARMN), and in silico examined their expression levels in different cell clusters under healthy and psoriasis conditions." (PMID 37822943, 2023). "We found that LINC01137, LINC01215, MAPKAPK5-AS1, TPT1-AS1, CARMN, CCDC18-AS1, EPB41L4A-AS, and LINC01214 may be potential diagnostic biomarkers for psoriasis." (PMID 33732554, 2021). "Our findings suggest that LINC01137, LINC01215, MAPKAPK5-AS1, TPT1-AS1, CARMN, CCDC18-AS1, EPB41L4A-AS, and LINC01214 may be potential diagnostic biomarkers for psoriasis and LINC01137, LINC01215, and LINC01214 may serve as predictive biomarkers for biologics response in psoriasis." (PMID 33732554, 2021).
chronic heart failure (1 paper, 2024). "This section explores the diverse pathological functions of CARMN, emphasizing its crucial role in the development of atherosclerosis, abdominal aortic aneurysm, chronic heart failure, Hirschsprung disease, airway stenosis, and various types of cancer." (PMID 39199342, 2024). "This evidence strongly suggests the potential of CARMN as a therapeutic target in the treatment of chronic heart failure." (PMID 39199342, 2024).
colon cancer (1 paper, 2024).
colorectal cancer (1 paper, 2024). A primary or metastatic malignant neoplasm that affects the colon or rectum. "CARMN was identified as a major regulator in colorectal cancer, directly demethylated by ALKBH5, thereby acting as a suppressive modulator of colorectal cancer proliferation and differentiation." (PMID 39039912, 2024).
ductal carcinoma in situ (1 paper, 2021). "In GSE21422, CARMN in ductal carcinoma in situ (DCIS) was lower than that in normal breast tissue and was obviously higher than that in invasive ductal carcinoma (IDC) at the same time." (PMID 34162418, 2021).
gastric cancer (1 paper, 2024). A primary or metastatic malignant neoplasm involving the stomach. "Concurrently, specific CARMN polymorphisms, particularly rs11168100 and rs353300, are significantly associated with gastric cancer (GC) risk, with rs11168100 showing a protective effect and rs353300 an increased risk." (PMID 39199342, 2024).
glioblastoma (1 paper, 2024). The most malignant astrocytic tumor (WHO grade IV). "In glioblastoma (GBM) tissues, the expression of CARMN is notably reduced, and higher levels of CARMN are associated with enhanced survival rates." (PMID 39199342, 2024).
cancer (7 papers, 2021 to 2024). A tumor composed of atypical neoplastic, often pleomorphic cells that invade other tissues. "Both upregulation and downregulation of lncRNAs involved in many physiological processes, such as MALAT1, PLUT, and CARMN, are associated with the onset of various cancers, as well as metabolic, cardiovascular, and neurological disorders." (PMID 33925370, 2021). "Furthermore, CARMN overexpression caused more failure of cytokinesis, indicating more cancer cells failed in successfully separated into two cells." (PMID 34162418, 2021). "Both in vitro and in vivo experiments revealed CARMN’s anti-oncogenic role in CC, consistent with its function in other cancers." (PMID 39558374, 2024). "CARMN mediates its anti-cancer effects through the inhibition of the Akt-mTOR and MAPK signaling pathways, as well as the suppression of autophagic flux." (PMID 39558374, 2024). "Therefore, CARMN acts as a tumor suppressor by negatively regulating miR-21, thereby curtailing the aggressive behavior of cancer cells." (PMID 39199342, 2024). "First, our RNA-seq showed CARMN may potentially regulated many cancer-related genes and pathways in which we only explored the most enriched pathway DNA replication and DNA replication related gene MCM5." (PMID 34162418, 2021). "KEGG pathway enrichment of DEGs indicated CARMN participates in various pathways correlate with both cisplatin action and tumorigenesis including DNA replication, cell cycle, base excision repair, mismatch repair and microRNAs in cancer etc.." (PMID 34162418, 2021). "In summary, lncRNAs (e.g., HOTAIR, CARMN, and LINC00478) may regulate cancer processes in multiple ways and be used as cancer biomarkers." (PMID 35740618, 2022). "In addition, involvement of CARMN, TPT1-AS1, and EPB41L4A-AS in cancer pathogenesis were reported." (PMID 33732554, 2021).
tumor (7 papers, 2020 to 2024). "Using this approach, the lncRNA CARMN (cardiac mesoderm enhancer-associated noncoding RNA, also known as MIR143HG), a host gene of the well-known tumor suppressor miR-143/145, was identified as a key modulator in the two modules associated with the NOR-CIN-CC transition." (PMID 39558374, 2024). "This suppression of MCM5, mediated by CARMN and miR-143-3p, inhibits DNA replication, leading to reduced tumor growth in triple-negative breast cancer (TNBC)." (PMID 39199342, 2024). "Next, we verified CRAMN’s expression in the TCGA-BRCA dataset, and the results showed that CARMN was significantly underexpressed in tumor samples." (PMID 36980514, 2023). "The expression of CARMN from The Cancer Genome Atlas (TCGA) and Genotype-Tissue Expression (GTEx) showed a significant downregulation in 16 out of 31 tumor type cohorts compared with corresponding normal tissues, especially for cervical squamous carcinoma (CESC)." (PMID 39558374, 2024). "The research further illustrated that CARMN functions as a tumor suppressor in EC." (PMID 39199342, 2024). "MiR-143/145 has reported to be co-transcribed with their host gene, CARMN, making it essential to determine whether miR-143/145 contributes to CARMN’s tumor suppressor function in CC." (PMID 39558374, 2024). "The expression analysis also showed that CARMN was highly expressed in the tumor samples." (PMID 36254230, 2022). "Besides, expression analysis showed that CARMN was highly expressed in the tumor samples." (PMID 36254230, 2022). "ALKBH5‐RIP assay identified lncRNA CARMN as a direct target of ALKBH5 in human tissue and mouse xenograft tumours." (PMID 39039912, 2024). "Subsequently, direct interaction between ALKBH5 and CARMN was confirmed via RIP assay in both human tissue and mouse xenograft tumours." (PMID 39039912, 2024). "In summary, we employed WGCNA to identify gene modules corresponding to the NOR-CIN-CC transition and discovered that CARMN functions as a hub gene and tumor suppressor in CC by modulating both ROS/Akt/mTOR and MAPK13-mediated MAPK signaling pathways." (PMID 39558374, 2024).
CARMN also shares sentences with these, for which no sentence is quoted: Hirschsprung disease (2 papers); abdominal aortic aneurysm (1); cardiovascular disease (1); infection (1); invasive ductal carcinoma (1); neurological disorders (1); rectal cancer (1); triple-negative breast carcinoma (1).